SHCBP1L (SHC binding and spindle associated 1 like)
Description:
Testis-specific spindle-associated factor that plays a role in spermatogenesis. In association with HSPA2, participates in the maintenance of spindle integrity during meiosis in male germ cells.
Synonyms: C1orf14; GE36
Tractability: No criterion of Open Targets' tractability assessment is met for any kind of drug.
Gene: Protein-coding gene on chromosome 1 (182,899,865 to 182,953,525, reverse strand). Ensembl gene ENSG00000157060.
Subcellular location: Cytoplasm, cytoskeleton, spindle
Gene Ontology:
Molecular function: protein binding
Biological process: male meiosis cytokinesis; positive regulation of chromosome organization; spermatogenesis
Cellular component: meiotic spindle; spindle
Genetic constraint (gnomAD): Loss-of-function variants: 52 observed, 51.26 expected, observed/expected ratio (o/e) 1.01, 90% interval 0.81 to 1.28. The upper end of that interval is the gene's LOEUF score, 1.28, which puts it in group 5 of 6, group 1 being the genes least tolerant of losing a copy. Missense variants: 731 observed, 716.19 expected, observed/expected ratio (o/e) 1.02, 90% interval 0.96 to 1.09. Synonymous variants: 260 observed, 262.99 expected, observed/expected ratio (o/e) 0.99, 90% interval 0.89 to 1.1.
Homologues: Orthologues: chimpanzee SHCBP1L (99% identical), macaque SHCBP1L (96% identical), pig SHCBP1L (88% identical), dog SHCBP1L (86% identical), mouse Shcbp1l (81% identical), rat Shcbp1l (81% identical), guinea pig SHCBP1L (73% identical). Paralogues in human: SHCBP1 (26% identical).
Diseases named in the same sentence as SHCBP1L in open-access papers:
SHCBP1L is named in the same sentence as 2 diseases in open-access papers, as found by Europe PMC text mining. Sharing a sentence is not in itself a finding about the gene and the disease.
SHCBP1L shares sentences with these, for which no sentence is quoted: tumor (1 paper); varicocele (1).